CCR2 (C-C motif chemokine receptor 2)
Diseases named in the same sentence as CCR2 in open-access papers (continued):
Sharing a sentence is not in itself a finding about the gene and the disease.
bladder cancer (13 papers, 2015 to 2024). "Moreover, the CCR2 -V64I polymorphism is potentially associated with the incidence of cancers including oral, cervical, and bladder cancers, while IL4 rs2243250 and rs79071878 have been linked to oncogenesis in certain cancers and ethnic groups." (PMID 38807156, 2024). "RS504393 is a selective CCR2 antagonist, which has shown strong antitumor activity in the mouse model of bladder cancer." (PMID 38468260, 2024). "It has been described that CCR2 antagonists in combination with anti-PD1 therapy leads to sensitization to anti-PD1 monotherapy in bladder carcinoma murine models." (PMID 36614248, 2023). "Mast cells in tumor microenvironment were reported to strengthen bladder cancer metastasis by regulating ERβ/CCL2/CCR2 EMT/MMP9 signals." (PMID 34112144, 2021). "In bladder cancer, CCL2/CCR2 interaction has been implicated in the stimulation of lymphoangiogenesis and development of lymphatic metastasis via macrophage tumor infiltration and VEGF-c production." (PMID 31811337, 2020). "So globally, mast cells promote metastasis of bladder cancer in mice in a CCL2/CCR2/EMT/MMP9‐dependent mechanism." (PMID 28599100, 2017). "Finally, in bladder cancer, mast cells induce EMT in cancer cells via stimulation of the ERβ/CCL2/CCR2 axis." (PMID 28599100, 2017).
coronary artery disease (13 papers, 2010 to 2025). "CCR2 has a crucial function in scavenger of CCL2 from the blood and a dysfunction in CCR2 is associated with early ischemic heart disease." (PMID 33918875, 2021). "The aim of the present study was to determine the association of the CCR2 Val64Ile polymorphism with the development of coronary artery disease in the WOSCOPS study sample set." (PMID 20181074, 2010). "clarified that the upregulation of CCR2 in PBMCs of HTLV‐1 infected patients with coronary artery disease exists." (PMID 40495291, 2025). "Our results are in accordance with previous studies reporting the anti-inflammatory actions of pioglitazone in coronary arteriosclerosis by reducing the expression of CCL2 receptor (CCR2) as well as in traumatic brain injury by modulating the PPARγ/NF-κB/IL-6 pathway." (PMID 37958504, 2023). "Both CX3CR1 and CCR2 are important in the development of coronary artery disease." (PMID 20836883, 2010). "This CCR2 association study does not confirm a role for the CCR2 Val64Ile polymorphism in the development of coronary artery disease." (PMID 20181074, 2010). "This case-control study does not support an association of the CCR2 Val64Ile polymorphism with coronary artery disease in the WOSCOPS sample set and does not confirm a possible protective role for CCR2 Val64Ile in the development of coronary artery disease." (PMID 20181074, 2010). "The chemokine receptors CCR2 and CX3CR1 are important in the development of coronary artery disease." (PMID 20836883, 2010). "Coronary artery disease (CAD) is an immune-mediated disease in which CCR2 attracts classical, intermediate, and non-classical monocytes to the arterial intima where they differentiate to macrophages." (PMID 38377416, 2020). "Therefore, our results further imply that CCR2 and CX3CR1 have independent, non-redundant roles in vascular inflammation and the later stages of coronary artery disease." (PMID 20836883, 2010).
infarction (13 papers, 2014 to 2025). A localised pathological necrosis of tissue resulting from obstruction of the blood supply usually by a thrombus, an embolus, or vascular torsion. "For example, in a model of ischemia reperfusion injury, C-C chemokine receptor type 2 (CCR2) deficient mice showed impaired monocyte and neutrophil chemoattraction and infiltration into the brain, with smaller infarction sizes, and reduced brain edema, which translated into neurological improvement." (PMID 32357544, 2020). "Although CCR2− (C‐C chemokine receptor type 2) resident macrophages are usually present in the heart, most die during infarction and are replaced by CCR2+ macrophages derived from infiltrating monocytes." (PMID 39761962, 2025). "In our previous study, a CCR2 inhibitor was found to increase the ratio of CCR2− macrophages, thereby strengthening the effects of adiponectin against myocardial injury after infarction." (PMID 38601146, 2024). "Knockdown of CCR2 reduces the recruitment of Ly-6Chigh monocytes to the infarct site, alleviates infarct inflammation, and inhibits post-infarction myocardial left ventricular remodeling, thereby promoting myocardial infarct healing." (PMID 36110847, 2022). "The silencing CCR2 moiety targeted the expression of CCR2 in Ly6Chigh inflammatory monocytes, reducing the accumulation of these cells during infarction, thereby enhancing the efficacy of MSC transplantation and myocardial remodeling." (PMID 32923434, 2020). "Monocytes/macrophages are recruited via CCL2/CCR2 axis, and deletion of CCR2 or CCL2 results in smaller cerebral infarcts, reduced monocytes/macrophages infiltration, and less proinflammatory mediator production, indicating a deleterious effect of these cells." (PMID 24877133, 2014). "In our study, infarct sizes, elastin deposition, and elastin areas were significantly smaller in MCP-1-KO than CCR2-KO mice 30 days post-MI and elastin was inversely related to MCP-1 expression during the 30-day recovery." (PMID 34040032, 2021). "The infarcted heart tissue attracts the inflammatory Ly6Chigh monocyte via CCR2+ within 30 minutes after induction of infarction through ligation of the left anterior descending (LAD) artery; hence, these CCR2+ receptors help in promoting and regulating inflammation." (PMID 32377427, 2020).
malaria (13 papers, 2009 to 2024). Malaria is a serious and sometimes fatal disease caused by a parasite that commonly infects a certain type of mosquito which feeds on humans. "In this context, migrating monocytes recruited to the spleen were found to be involved in the control of blood stage malaria, in CCR2-dependent fashion." (PMID 28181563, 2017). "Patients' MO had significantly lower percentages of CD56 and mIFN-γ and higher percentages of CCR2+CX3CR1+ than malaria-exposed individuals, and high expression of the inflammatory marker TREM-1." (PMID 19851453, 2009). "In healthy malaria exposed individuals, the percentage of CD14hi CCR2+CX3CR1+ MO was low (mean value: 5.23±4.49%, 95% CI: 1.84–8.62)." (PMID 19851453, 2009). "In addition, CCR2 KO mice were used to investigate the role of CCR2-dependent monocytes in the development and the resolution of malaria-induced lung pathology." (PMID 33664739, 2020). "It was previously shown in the P. chabaudi rodent model of malaria that inflammatory monocytes migrate to spleens, in CCR2 dependent manner, where they are important effector cells implicated in the control of parasite burden, likely through their phagocytic activity and release of ROS." (PMID 25233271, 2014). "The reduced control of parasitaemia observed in CCR2−/− mice correlated with significantly lower numbers of inflammatory monocytes in the spleen of these animals, suggesting these cells play a role in controlling blood-stage malaria." (PMID 24476686, 2014). "In malaria, both CXCL10 and CCL2 serum protein levels increased reaching peak levels between day 4 and 7 after infection whereas CCL7 was constitutively deregulated in Ccr2-deficient animals." (PMID 23762028, 2013). "Furthermore, the resolution of malaria-induced lung pathology is mediated by unknown CCR2-independent mechanisms." (PMID 33664739, 2020). "FACS analysis of 2 important chemokine receptors known to promote T cell chemotaxis to inflamed tissues, such as CCR2 and CCR5, which are known to be involved in the development of severe malaria and CM, respectively, was performed." (PMID 23646169, 2013). "The mean level of CCR2 and CX3CR1 expression on the total blood MO was three times higher in patients with acute uncomplicated malaria (18.5±1.5%) than in healthy malaria exposed individuals (6.0±4.8%)." (PMID 19851453, 2009). "Chemotaxis to CCL2 and expression of CCR2 by neutrophils were minimal and not altered in malaria patients." (PMID 22745844, 2012). "Additionally, mice lacking CCR2 were completely susceptible to cerebral malaria, highlighting the importance of MCP-1/CCL-2 in malaria pathophysiology." (PMID 39567619, 2024). "The pre-clinical study demonstrated that CCR2 expression was significantly upregulated by CD8 + T cells isolated from the brain and spleen of malaria-infected mice, suggesting that trafficking through these chemokine receptors may be involved in recruiting inflammatory cells during severe malaria." (PMID 39567619, 2024). "CD8+ T cells isolated from the spleen and brain of malaria-infected mice significantly upregulated CCR5, CCR2, CXCR4 and CXCR3 expression, initially suggesting that trafficking via these chemokine receptors could be involved in the recruitment of inflammatory cells during severe disease." (PMID 24476686, 2014). "Hence, there remains the possibility that the lack of progenitor mobilization in Ifngr1- and Ccr2-null animals during acute malaria is not fully reflecting the situation in wild type hosts, a crucial question for future studies." (PMID 23762028, 2013). "However, the significance of our findings in the pathogenesis of malaria is not yet clear, because it has been shown that CCR2 signaling does not have any influence on the development of CM in mice." (PMID 23646169, 2013).
malaria (continued). "Despite this transformation, absence of CCR2 completely abolished the disappearance of BM myeloid progenitors, for both “CD27+ CMPs” (60.6±5.0×103 cells uninfected, 50.7±7.2×103 cells day 7 p.i.)and “GMPs” (41.8±8.4×103 cells uninfected, 59.3±6.5×103 cells day 7 p.i.), during acute malaria." (PMID 23762028, 2013).
peritonitis (13 papers, 2010 to 2024). Inflammation of the peritoneum (tissue that lines the abdominal wall and covers most of the organs in the abdomen). "We used a thioglycolate-induced peritonitis model to demonstrate a role for CCR2/MCP-1 in trafficking of CCR2+ cells to an inflammatory site, and showed the ability of a CCR2 antagonist to inhibit such trafficking." (PMID 33322474, 2020). "In dialysis-induced peritonitis, CCR2+ mo-Mac are increased in the peritoneal cavity as compared to normal dialysis." (PMID 31456804, 2019). "We compared transfer of hCD68GFP versus hCD68GFP/CCR2−/− monocytes into wild-type recipient animals with zymosan-induced peritonitis." (PMID 27908893, 2017). "We have recently demonstrated that CCR2−/− mice also show a significant reduction in the number of neutrophils recruited in the zymosan peritonitis model, although this effect is of a much small magnitude to that seen on monocyte recruitment." (PMID 26620767, 2015). "CCR2 ligation was previously shown to be essential for monocyte recruitment and differentiation to macrophages during low-grade (0.1 mg/mouse) zymosan A-induced peritonitis." (PMID 32296415, 2020). "Moreover, CCR2 WT BMCs were recruited more efficiently in early phases after induction of peritonitis than CCR2 KO cells." (PMID 29867927, 2018). "Then, we asked whether attenuated migration of HSPCs in CCR2 KO mice with peritonitis had an impact on the emergence of peritoneal ILCs." (PMID 30233592, 2018). "Several studies indicate that Ccl2 and Ccl7 are the primary agonists of Ccr2, in which ablation of either of these ligands reduced monocyte recruitment from bone marrow to peripheral vessels in thioglycollate-induced peritonitis and Listeria monocytogenes infection." (PMID 25595590, 2015). "MCP-1 levels in plasma and macrophage secretions of Sgpl1−/− chimeras were considerably reduced, while these chimeras also showed diminished peritoneal influx of CCR2-positive F4/80 macrophages in a model of MCP-1-dependent peritonitis, which points to aberrant macrophage migratory response." (PMID 23700419, 2013). "To investigate the relative contributions of CCR2 and CX3CR1 to monocyte/macrophage recruitment in vivo, we used a mouse model of thioglycollate-induced peritonitis." (PMID 21060874, 2010). "Thus, we performed the thioglycollate-induced peritonitis in heterozygous mice with a florescent gene report for chemokine receptors CX3CR1+/GFP (green) and CCR2+/RFP (red) in inbred mice strains CCR2+/RFP CX3CR1+/GFP." (PMID 28824619, 2017).
lymphoma (12 papers, 2011 to 2025). A malignant (clonal) proliferation of B- lymphocytes or T- lymphocytes which involves the lymph nodes, bone marrow and/or extranodal sites. "The CCL2-CCR2 axis was also linked to tumor progression in a spontaneous model of lymphoma; accordingly, genetic ablation of Ccr2 inhibited tumor growth." (PMID 37342322, 2023). "They further revealed that the tumor-promoting effects of BM- or lymphoma-derived MSCs were due to CCR2-mediated recruitment of CD11b+Ly6C+ monocytes." (PMID 29029511, 2017). "Since the truncated CCL2 domain of GMME1 is only active on CCR2, we determined the pharmacological effect of the fusokine on the EG7 mouse lymphoma cell line known to express CCR2." (PMID 21943176, 2011). "We found that distinct to full length CCL2 or its N-truncated derivative (CCL2 5-76), GMME1 bound to CCR2 on mouse lymphoma EG7, human multiple myeloma cell line U266, or murine and human medulloblastoma cell lines, and led to their death by apoptosis." (PMID 21943176, 2011). "In an in vivo study using lymphoma-grafted mice administered systemically, the CCR2 (which is a chemokine receptor) gene was targeted by siRNA, which inhibited its deposition in the sites of inflammation, by degrading the CCR2 mRNA in monocytes." (PMID 40860190, 2025). "In addition, It has been shown that MSCs isolated from spontaneous lymphomas in mice (L-MSCs) were more effective in recruiting monocytes/macrophages and in promoting tumor growth than BM-MSCs and their activity was mediated via C-C-Chemokine receptor type 2 (CCR2)." (PMID 29069870, 2017). "In addition to CD68 and CD163, S100A9, CCR2, CD32, CD36, and Slan were also critical in the characterization of lymphoma‐specific tumor macrophages." (PMID 33135337, 2020).
Autoimmunity (11 papers, 2011 to 2024). The occurrence of an immune reaction against the organism's own cells or tissues. "In this study, both mTORC1 and STAT1 signalling were enhanced in CCR2‐deficient mice, promoting B‐cell metabolism and transcriptional signalling, thus suggesting the role of this mechanism in autoimmunity." (PMID 35875970, 2022). "This is reminiscent of prior studies indicating that CCR2 signaling increases the fitness of Treg cells, and CCR2 deficiency renders Treg cells functionally inferior to wild-type counterparts in suppressing autoimmunity after they are locally transferred to allograft tissue sites." (PMID 39528947, 2024). "We recently demonstrated that ablation of the CCR2 gene exacerbated the pathology of polyarthritis spontaneously developed in IL-1 receptor antagonist-deficient mice, suggesting its immune regulatory roles in autoimmunity." (PMID 22815949, 2012). "Collectively, CCR2 plays a crucial part in regulating B‐cell peripheral differentiation and maintaining the integrity of peripheral autoimmunity." (PMID 35875970, 2022). "CCR2 expression is maintained and drives homing of activated γδT17 cells to inflamed tissue during autoimmunity, cancer and infection." (PMID 28580944, 2017). "While CCR6 recruits resting γδT17 cells to the dermis, CCR2 drives rapid γδT17 cell recruitment to inflamed tissues during autoimmunity, cancer and infection." (PMID 28580944, 2017). "In contrast, CCR2 was not expressed despite previously being linked with γδ T cell recruitment during inflammation and autoimmunity." (PMID 38215167, 2024). "In this study, the reduced expression of CCR2 in peripheral B cells of SLE patients was noticed, and the metabolic activity of B cells in CCR2‐deficient mice was significantly increased, thus promoting the development of autoimmunity." (PMID 35875970, 2022). "Consequently, deletion of CCR2+ monocytes/macrophages profoundly reduces immunity to infection and autoimmunity." (PMID 34804061, 2021). "Similarly, deletion of CCR2+ monocytes has a profound impact on immunity to infection and autoimmunity." (PMID 34804061, 2021). "Similarly, the Mildner study showed that the selective depletion of CCR2+Ly6Chi monocytes strongly reduced the CNS autoimmunity, indicating a disease-promoting role of CCR2+Ly6Chi monocytes during autoimmune inflammation of the CNS." (PMID 30670926, 2018). "Our data that monocytes were missing from the spleen while remained abundant in the bone marrow and joints of immunized CCR2−/− mice suggest that there is a potential link between CCR2-expressing monocytes and Th17 cells during autoimmunity." (PMID 21991368, 2011). "Chemokine (C‐C motif) receptor 2 (CCR2) interacts with its ligand CCL2 at different expression levels to induce the recruitment of chemotactic cells to tissues, maintain immune homeostasis and regulate autoimmunity." (PMID 35875970, 2022). "In EAE the absence of CCR2+ monocytes decrease disease severity, indicating a role for CCR2+ monocytes in both CNS neuroinflammation and autoimmunity." (PMID 31552027, 2019). "In models of autoimmunity, cancer and infection, activation-induced downregulation of CCR6 releases γδT17 cells from their homeostatic immunosurveillance trafficking circuit through the skin and circulation, which then enhances their CCR2-dependent homing to inflamed tissue." (PMID 28580944, 2017).